APC (APC regulator of Wnt signaling pathway)
Diseases named in the same sentence as APC in open-access papers (continued):
Sharing a sentence is not in itself a finding about the gene and the disease.
colorectal cancer (continued). "Inactivation of the APC gene plays a crucial role in the development and progression of colorectal cancer, while APC gene alterations are rare in sarcomas." (PMID 38903727, 2024). "Pathogenic TE insertions are associated with various hereditary cancers, including hereditary breast and ovarian cancer syndrome (BRCA1, BRCA2, and BARD1); Lynch syndrome (MLH1); and colorectal cancer (APC)." (PMID 39697868, 2024). "These mutations are frequently seen in colorectal cancer, whereas KRAS, PIK3CA, and APC mutations are rarely observed in prostate cancer." (PMID 39902031, 2024). "While usually SMAD4 loss alone does not initiate tumor formation, it promotes progression after cancer is initiated by other oncogenes like KRAS in PDAC and APC in colorectal cancer." (PMID 38666907, 2024). "Despite a low prevalence of APC mutations compared with non-CDX2-suppressed colorectal cancers, CDX2-suppressed cancers showed a higher prevalence of mutations in several other components of the WNT/APC/β-catenin pathway." (PMID 39452477, 2024). "APC mutant colorectal cancer cells secrete WNT antagonists such as NOTUM, which repress wild-type ISCs." (PMID 39060237, 2024). "Nevertheless, truncating driver APC mutations are enriched in metastatic Class 1 CRC vs. primary Class 1 CRC, which highlights the importance of these loss-of-function mutations in colorectal cancer progression." (PMID 38275886, 2024). "The potential lipid metabolism targets for therapeutic intervention in APC-driven colorectal cancer." (PMID 38590663, 2024). "Nine colorectal-cancer-related mutations are detected on the root branch of the tree, including in APC, a well-recognized initiator gene in colorectal cancer." (PMID 38685065, 2024). "Efforts to increase APC concentration through APC-expressing liposomes have shown success in reducing colorectal cancer occurrence in APC-min mice." (PMID 39766864, 2024). "The best example is the LINE-1 insertions into the APC locus leading to low expression levels of its gene product, ultimately driving colorectal cancer." (PMID 38247798, 2024). "In colorectal cancer, APC was the most common comutated gene as expected; however, Groups 1 and 4 APC mutations were typically nonsense and frameshift while Groups 2 and 3 mutations were missense." (PMID 38282550, 2024). "TMEM9 promotes lysosome activation, and in turn facilitates the degradation of APC, which releases β-catenin and activates Wnt-signalling in liver cancer and colorectal cancer." (PMID 38965614, 2024).
colorectal cancer (continued). "Multiple driver genes of relatively high prevalence in other cancer types were associated with race, including an increased frequency of KRAS and PTEN mutations but decreased prevalence of APC and BRAF mutations in Black patients with colorectal cancer." (PMID 38297963, 2024). "Our data establish a role for APC in coordinating actin with cell adhesion dynamics to control collective cell remodeling and directed cell motility in colorectal cancer." (PMID 37128612, 2023). "Apart from CRC caused by CpG island methylator phenotype (CIMP) or mismatch repair hypermutable microsatellite instability (MSI) phenotype, alterations in the APC gene are the initiator of over 85% of sporadic colorectal cancers." (PMID 38004598, 2023). "Due to the presence of genetic variants in the APC gene/β-catenin pathway in patients with PACC, chemotherapy regimens known to be active in PDAC or colorectal cancer are often used clinically." (PMID 37465113, 2023). "Studies have shown that miR-135a and miR-135b can directly target and downregulate APC, which is a critical event in the early stages of colorectal cancer." (PMID 37465677, 2023). "To further validate our results, we also measured the cell size in the SW480 colorectal cancer cell line in which the endogenous APC lacks the C-terminal region (where the actin-related function resides)." (PMID 37128612, 2023). "Mutations of the APC, TTN, MUC16, and KRAS genes were high in frequency in both colorectal adenoma and colorectal cancer samples." (PMID 37546388, 2023). "Germline mutations in the adenomatous polyposis coli (APC) tumor suppressor gene are found in Familial Adenomatous Polyposis (FAP); somatic APC mutations are found in the vast majority of sporadic colorectal cancers." (PMID 37046763, 2023). "APC constitutively activates the canonical WNT signaling in most colorectal cancer cases, leading to cell proliferation and tumor formation." (PMID 38062391, 2023). "Here, we show that expression of APC-m4 in colorectal cancer cells led to a reduction in F-actin at cell junctions relative to the levels observed in cells expressing APC-WT." (PMID 37128612, 2023). "SW480 colorectal cancer cell line expresses a truncated version of APC (1–1388 amino acids), and therefore lacks the C-terminal domain of the protein, where the cytoskeleton activity resides." (PMID 37128612, 2023).
colorectal cancer (continued). "In colorectal cancer, the levels of miR-135a and miR-135b are upregulated and are inversely correlated with the levels of APC." (PMID 37465677, 2023). "Germline mutations in the APC gene located on chromosome 5q 21–22 can lead to familial adenomatous polyposis (FAP) and the development of colorectal cancer (CRC) if left untreated." (PMID 36864485, 2023). "This study’s findings are expected to contribute to increasing the accuracy of drug-response prediction in patient-derived APC mutant colorectal cancer organoids, thereby providing reliable precision medicine and improving patient survival rates." (PMID 38067236, 2023). "Third, the ROS signature SBS18 was enriched in SGMs in one gene, APC, which was identified in metastatic colorectal cancers of the HMF cohort (27 of 346 SGMs versus 1 expected; P = 2.2 × 10−31)." (PMID 37922356, 2023). "This is line with the results that the alternations of APC is an early driver event that accounts for 80% of colorectal cancers." (PMID 37368936, 2023). "T The Wnt/β-catenin pathway is known to have a pivotal role in the early development of colorectal cancer, with deactivation of the APC gene being a crucial factor leading to the release of β-catenin and activation of the Wnt pathway." (PMID 37465677, 2023). "With regard to the carcinogenesis, it is noteworthy that the colorectal carcinoma of the index patient carried pathogenic APC and KRAS mutations as observed in conventional sporadic and FAP- and MAP-related colorectal carcinomas." (PMID 35675019, 2023). "About 20% of colorectal cancer cases have a genetic base as it occurs in FAP patients, a syndrome caused by a mutation in the APC gene." (PMID 35804854, 2022). "Genetic variants in APC have been implicated in familial adenomatous polyposis (FAP) and colorectal cancer (Fodde R, 2002)." (PMID 36324892, 2022). "More than 60% of patients with early colorectal cancer had mutant APC DNA molecules at levels ranging from 0.01 to 1.7 percent of the total APC molecules." (PMID 35159010, 2022). "Colorectal cancers contain many mutations in the Wnt/β-catenin signaling pathway genes upstream of TNIK, such as the adenomatous polyposis coli (APC) tumor suppressor gene." (PMID 36361804, 2022). "Mutations in APC can cause familial adenomatous polyposis (FAP), the main hereditary factor in colorectal cancer." (PMID 36230711, 2022).
colorectal cancer (continued). "The adenomatous polyposis coli (APC) play a rate-limiting role in the majority of sporadic colorectal cancers." (PMID 35057823, 2022). "Adenomatous polyposis coli (APC) is a tumor suppressor whose mutations underlie familial adenomatous polyposis (FAP) and colorectal cancer." (PMID 35417240, 2022). "Nuclear β-catenin accumulation in APC-mutant colorectal cancers is therapeutically relevant given itscentral role in Wnt signaling." (PMID 36589880, 2022). "Most driver genes were only found in single cancer types and represented key disease-specific drivers such as EGFR and TERT in glioma, MYC in BNHL, and APC in colorectal cancer." (PMID 35947558, 2022). "As a result, the study proved that advanced colorectal cancer corresponds with the presence of mutant adenomatous polyposis coli (APC) DNA molecules in blood plasma." (PMID 35159010, 2022). "We next examined the dependence of β-catenin nuclear localization on TNPO1/2 in colorectal cancer cell lines, HCT-116 and DLD-1, which harbor an activating Ser45 β-catenin mutation and a deactivating frameshift mutation in APC, respectively." (PMID 36300792, 2022). "With the exception of LOVO colorectal cancer cell line, the APC mutant cell lines responded to the treatment with the PP and ABT737 combination with a shift in the EC50 towards the left of the cytotoxicity curve, that is increased sensitivity to PP." (PMID 35301819, 2022). "Examples of tumor initiation that are likely mediated by REs come from several studies with the most convincing ones observed in colorectal cancer where independent reports of insertions in the well-known tumor driver APC gene were found in several patients." (PMID 35163677, 2022). "Alternatively, point mutations of the β-catenin coding gene CTNNB1 lead to alterations in the protein’s N-terminal Ser/Thr phosphorylation sites, thereby preventing phosphorylation by GSK3β and consequent degradation in some APC wild-type colorectal cancers." (PMID 35663403, 2022). "Alterations in APC, for instance, account for only 2.4% of breast cancer cases, compared to a staggering 73% of colorectal cancers." (PMID 35663403, 2022). "This highlights the importance of the Hippo/YAP pathway in RNF43-mutant pancreatic cancer and is consistent with the observation of YAP dependency in APC/CTNNB1-mutant colorectal cancers." (PMID 35536676, 2022). "Colorectal SRCC is a rare subtype of colorectal cancer with distinctive molecular characteristics, including a low incidence of KRAS, PIK3CA, and APC mutations." (PMID 34997025, 2022). "Other examples include microRNAs miR-135a and miR-135b that directly repress APC expression in colorectal cancer cells, thereby destabilizing the β-catenin destruction complex and allowing Wnt target gene expression." (PMID 35116092, 2022). "Heterozygous APC germline mutations predispose to familial adenomatous polyposis (FAP) syndrome and a lifetime risk for colorectal cancer." (PMID 36531003, 2022). "The ‘Mutated in Colorectal Cancer’ (MCC) gene was discovered due to its close proximity to the APC gene on chromosome 5, but it has APC-independent roles in colorectal cancer." (PMID 35740525, 2022).
colorectal cancer (continued). "Inhibition of the APC protein activity leads to unregulated cell progression, which has been extensively studied and described for example in colorectal cancer." (PMID 36012171, 2022). "The reduction in APC truncated protein through RNA interference technology decreases the proliferation of six types of colorectal cancer cells and decreases tumor growth in vivo." (PMID 36432565, 2022). "Inactivation of the adenomatous polyposis coli (APC) gene is frequently observed in colorectal carcinoma." (PMID 36289675, 2022). "The tumor suppressor gene (TSGene) APC has been most studied in colorectal cancer, and its role in liver cancer has also been reported." (PMID 35111672, 2021). "UbcH10, the E2 ubiquitin ligase of APC, is highly expressed in colorectal cancer and was suggested to act as an oncogene by promoting cell division through APC." (PMID 34356615, 2021). "In colorectal cancer, APC is a well-established tumor suppressor, and its inactivation is a common mechanism of colorectal tumorigenesis." (PMID 34540821, 2021). "The comparison of clinical variable-associated mutation genes between the two ethnic groups showed little overlap, and only a few key colorectal cancer genes such as APC and JAK1 were common." (PMID 35003350, 2021). "APC is an important tumor suppressor protein in the Wnt signaling pathway and mediates the development of colorectal cancer." (PMID 33954154, 2021). "APC is a component of the Wnt signaling-APC/Axin destruction complex and a well-established tumor suppressor in human colorectal cancer." (PMID 33572709, 2021). "Loss of function mutations in the tumor suppressor adenomatous polyposis coli protein (APC) pre-disposes to colorectal adenomas and colorectal cancer, and the vast majority of sporadic colon tumors are found to have mutations in APC." (PMID 34638991, 2021). "The expression of miR-494 is upregulated in colorectal cancer tissues, and this miRNA can promote cancer progression by negatively regulating adenomatous polyposis coli (APC)." (PMID 33435156, 2021). "Most colorectal cancers (CRC) are initiated by mutations activating the Wnt/β-catenin pathway, commonly in the APC gene." (PMID 34359960, 2021).